CCND1 (cyclin D1)
Diseases named in the same sentence as CCND1 in open-access papers (continued):
Sharing a sentence is not in itself a finding about the gene and the disease.
tumor (continued). "Hosokawa and Arnold found two tumor cell lines in which a mutant allele of cyclin D1 is amplified but the wild-type copy is not." (PMID 16322765, 2005). "The discovery that increased levels of cyclin D1 and cyclin E promote cell growth by shortening the G1 phase led to the postulation that overexpression of those cyclins is positively involved in carcinogenesis and possibly in clinical tumour aggressiveness." (PMID 15292923, 2004). "With the new cut-off, 15 (11.2%) of the 134 tumours tested here showed CCND1 amplification." (PMID 11870541, 2002). "or more were considered to reflect overexpression of the CCND1 gene in tumour RNA samples." (PMID 11870541, 2002). "Twenty-four out of 30 (80%) RP tumours had an increase in CCND1 (range 2.11 to 9.00)." (PMID 12237776, 2002). "CCND1 amplification might simply be an additional mechanism contributing to high levels of CCND1 overexpression observed in oestrogen receptor-positive tumours, through a simple gene dosage effect." (PMID 11870541, 2002). "Indeed, the good outcome of patients with CCND1-overexpressing tumours was reverted by CCND1 amplification." (PMID 11870541, 2002). "It is noteworthy that most CCND1-overexpressing tumours are oestrogen receptor-positive." (PMID 11870541, 2002). "Ki67 expression was significantly associated with increasing tumour stage (P< 0.005) and histological grade (P< 0.05) but did not correlate with cyclin D1 expression." (PMID 11161387, 2001). "In addition, there was a significantly higher progression rate for those patients with Ta/T1 disease whose tumours demonstrated cytoplasmic cyclin D1 staining." (PMID 11161387, 2001). "Positive staining for cyclin D1 was found in 83% of tumours." (PMID 11161387, 2001). "In addition, the median value for cyclin D1 staining was significantly higher in G1/G2 tumours (43%) compared with G3 tumours (14%, P< 0.005)." (PMID 11161387, 2001). "Cyclin D1 was overexpressed in both borderline and invasive tumours." (PMID 10584879, 1999). "However, in tumours overexpressing cyclin D1 (n = 72), the proportion displaying exclusively cytoplasmic localization of protein was higher in those with serous compared with non-serous histology (P = 0.004, odds ratio 4.8, 95% confidence interval 1.4–19.1)." (PMID 10584879, 1999). "Moreover, eight benign lesions, two borderline tumours and 11 carcinomas proved to be suitable for the analysis of cyclin D1 transcript, and emerging data demonstrated significant agreement between protein abundance and mRNA expression." (PMID 9155044, 1997). "However, highly elevated CDK4 mRNA levels, compared with that seen in a panel of normal tissues, were observed in 76% of the tumours, accompanied in 71% of the cases by high expression of the CCND1 cyclin activator." (PMID 8611425, 1996). "The relative risk of local relapse was 9.1 in tumours without cyclin D1 overexpression (P = 0.01, Cox regression analysis)." (PMID 8562333, 1996). "CCND1 is amplified in 54% and overexpressed in 63% of the tumours of the squamous cell type." (PMID 7819051, 1995). "Targeting these dysregulated cell cycle pathways holds promise for cancer therapies, such as restoring normal cell cycle checkpoints or inhibiting key regulatory proteins such as cyclin D1, which could potentially halt tumor growth and reduce cancer progression." (PMID 40723282, 2025). "Additionally, tumor cells that survive HER2 blockade retain high expression of cyclin D1.18,25 These studies suggest that cell cycle activity may be associated with resistance to HER2-targeted therapies." (PMID 41016944, 2025). "Consequently, we concluded that X26nt could increase CCND1 expression and promote tumor growth in vivo." (PMID 40697992, 2025).
tumor (continued). "Interestingly, although tumor size decreased in the palbociclib group, CCND1 expression was slightly higher than in the control group, further supporting the notion that increased CCND1 expression may contribute to palbociclib resistance." (PMID 41271634, 2025). "Furthermore, we examined expression of the c-myc and cyclin D1 genes in the tumor tissues." (PMID 40895532, 2025). "The association with ERBB signaling pathways among negatively correlated genes points to a potential compensatory mechanism in more aggressive tumor subtypes, where alternative oncogenic pathways might become activated in response to changes in CCND1 expression." (PMID 39940659, 2025). "In addition, this approach could inhibit tumor progression by disrupting the cyclin D1–driven proliferation of cancer cells." (PMID 40408472, 2025). "Additionally, the enrichment of immune-related pathways raises the possibility that CCND1 plays a role in shaping the tumor immune microenvironment, which could impact immune surveillance and response to therapies." (PMID 39940659, 2025). "Therefore, it is critical to elucidate the relationship between the CDK4/6–cyclin D1 complex and the tumor microenvironment components after CDK4/6i treatment, namely, how these inhibitors induce favorable immunotherapeutic effects, or the reverse, in patients." (PMID 39593745, 2024). "This difference could be attributed to the elevated levels of cyclin D1 in tumor cell lines." (PMID 38571493, 2024). "Indeed, correlations between cyclin D1 immunostaining and the Ki67 LI and tumor volume and cavernous sinus invasion were observed on a representative series of PT including NFPT but not specifically detailed in this subgroup, and the same occurred in a subgroup of aggressive PT." (PMID 38095839, 2024). "Therefore, we performed interphase FISH on four available tumor samples with CCND1-ecDNA." (PMID 39267784, 2024). "In addition, all seven patients showed Cyclin D1 expression in their tumor samples." (PMID 39411551, 2024). "Moreover, through RNA sequencing analysis in tumor CD8+ T cells, we found that genes associated with effector functions, such as Sox6, Ccnd1, CD81 and Trim14, were upregulated, while genes associated with immune inhibition, such as Tox, Jun-b, Btla, Batf and Foxp1 were downregulated 25-27." (PMID 38994031, 2024). "Three ginsenoside derivatives, xl, 1c, and 8b, showed good anti-tumor activity against LC, and their anti-growth activity against LC cells partly involved β-catenin-mediated signaling, as these substances reduced the expression of β-catenin and its subsequent targets CCND1, CDK4, and Myc." (PMID 37841927, 2023). "The p16 protein plays a role as a tumor suppressor that negatively regulates the cell cycle by inhibiting the activity of cyclin D-dependent kinases to prevent phosphorylation of the RB family protein and cyclin D1 bind to cdk4, leading to the inactivation of RB genes." (PMID 35876683, 2023). "Furthermore, cyclin D1 overexpression was postulated to represent an independentprognostic risk factor in OSCC as it showed significant associations with LNM, tumor celldifferentiation, and tumor stage in some populations." (PMID 36716784, 2023).
tumor (continued). "Significantly, in the early stages of tumour development, both NFKB1/RELA and PIEZO1 displayed heightened expression levels, paralleled by similar kinetic trends of proliferation‐associated genes such as CDK6, CCND1 and CCND3, as unveiled by functional pseudotime analysis of the scRNA‐seq dataset." (PMID 37983931, 2023). "Furthermore, a coordinated effect between c-Myc and cyclin D1 may drive tumor aggressiveness and accelerate disease progression." (PMID 37064948, 2023). "While in normal cells, this would lead to cell cycle arrest, activating mutations in BRAF and NRAS, combined with mutation in tumor suppressors such as PTEN and can result in robust mitogenic signaling and translation of CCND1, which may “override” CDKN1A/p21-mediated checkpoint activation." (PMID 36696495, 2023). "Increased cyclin D1 expression could enhance tumor growth by disrupting cell cycle control." (PMID 36771561, 2023). "Furthermore, cyclin D1, a crucial regulator of normal cell cycle and cancer progression, responds to diverse cellular signaling pathways, and its overexpression contributes to tumorigenesis by promoting cell proliferation and tumor growth." (PMID 37535222, 2023). "Also, compared to carnosine solution, P-Liquisomes had a stronger chemopreventive impact, as shown by a decrease in tumor growth, an increase in the ratio of tumor growth inhibition %, vascular endothelial growth factor levels, cyclin D1 levels, and caspase-3 levels, and a decrease in tumor size." (PMID 37808196, 2023). "In addition, our results showed that CXCL3 overexpression also exerts its role to regulate Bcl-2, Bcl-2/Bax and Cyclin D1 expression that are responsible for apoptosis and cell cycle, the processes upon which tumor cells depend for proliferation, survival, and metastasis." (PMID 38031087, 2023). "Similarly, combinations of Fgfr2FL with Myc, Fgf3 and/or Ccnd1 cDNAs into single lentiviral constructs cooperatively shortened tumour onset after intraductal delivery, with the latencies of the Fgfr2FL-T2A-Myc and Fgfr2FL-T2A-Fgf3-P2A-Ccnd1 combinations matching Fgfr2ΔE18 single-driver latency." (PMID 35948633, 2022). "Additionally, it was demonstrated that overexpression of CCND1 or c-Myc could invalidate the tumor-inhibiting effects of CDC42EP3 knockdown." (PMID 35365622, 2022). "Finally, CCND1 was amplified in 1 primary tumor (5%) and 1 CM (5%)." (PMID 35267459, 2022). "Further research found that both endogenous and exogenous miR-139-5p may limit the proliferation of F. nucleatum-related CRC by provoking tumor-specific proteins, such as c-Myc and cyclin D1, demonstrating the potential therapeutic value of endogenous or exogenous miRNA in CRC." (PMID 36110534, 2022). "In the study of The Cancer Genome Atlas Network for HNSCC, the percentages (%) of PTEN genetic alterations in HPV (+) and HPV (-) tumours were 12% and 6%, respectively, and either PTEN mutation or inhibition could result in PIK3CA/CCND1/CDK6 pathway activation and thereby enhance cell proliferation." (PMID 35421166, 2022). "Tumor suppressor activity of CHREBP could be affected by the upregulation of cyclin D1." (PMID 35768405, 2022). "In addition, PPP1CA can bind to cyclin D1 to phosphorylate RB or can dephosphorylate breast cancer susceptibility protein-1 (BRCA1), all of which induce cell cycle deregulation and promote tumor cell proliferation." (PMID 34964699, 2022). "Furthermore, the compound inhibits tumor cells proliferation in the athymic xenograft mice model, without any apparent toxicity yet suppressing the expression of Wnt target genes associated with tumor growth, including MYC (c-myc), CCND1 (cyclin D1), and BIRC5 (survivin)." (PMID 35053565, 2022). "In addition, cyclin D1 is demanded for the production and maintenance of tumor." (PMID 36157053, 2022). "Moreover, this cluster tumor is associated with amplified TERC, TERT, MYC, CCND1, and BCL2L1." (PMID 34815793, 2021).
tumor (continued). "An enhanced macrophage infiltration into EwS tumors following the transfer of PRKCB and CCND1 transcripts could promote tumor growth, potentially by increasing the density of macrophages in tumors to amplify the immunosuppressive effects of their proinflammatory cytokines triggered by EZH2 and DKK2." (PMID 34604225, 2021). "In addition, the mice tumor tissues were collected and prepared, and our following results indicated that the expression levels of Cyclin D1 and CDK2 (P < 0.05), and Ki67 were decreased, while Caspase-3 and Bax were increased (P < 0.05) by co-treating CR-GC cells with DB and cisplatin." (PMID 33579380, 2021). "Cyclin D1 can serve both to activate and downregulate gene expression as a transcriptional role directly binding with genome DNA, which means that cyclin D1 may be a key protein during oncogenesis and tumor development." (PMID 34335935, 2021). "We speculate that cyclin D1 play a major role to promote tumor cell invasion and metastasis." (PMID 34539418, 2021). "Also, based on the key cellular functions of cyclin D1 in driving cell cycle progression, we further propose that downregulation of cyclin D1 by zotatifin contributes to the strong anti-tumor activity of zotatifin and to the effectiveness of combination treatments with PI3K or AKT inhibitors." (PMID 34900714, 2021). "In addition, CM from IL1β-treated fibroblasts induces the overexpression of Cyclin D1 and cMyc, which might help explain how IL1β-soluble targets influence the cell-cycle progression and chemoresistance observed in tumor cells, when treated with L-OHP." (PMID 34066976, 2021). "Meanwhile, IFN-beta-WJMSCs and IFN-beta-hBMMSCs exhibited the ability to suppress tumor growth in bronchioloalveolar carcinomas and HCCs, respectively, the latter exerting its effect by increasing expression of p21, p27 and FOXO3a, as well as decreasing protein levels of cyclin D1, pRb and AKT." (PMID 33849537, 2021). "The inhibited expression of Cyclin D1 may lead to cell cycle arrest and tumor formation." (PMID 33571243, 2021). "Moreover, under drug‐mediated pressure, NF‐κB might cooperate with other signaling pathways to regulate pro‐survival genes (such as cyclin D1 and Bcl‐2) and upregulate the transcription of the genes, which helps tumor cells to develop drug resistance." (PMID 34977871, 2021). "Furthermore, the xenograft tumor-bearing mice models were established, and we proved that knock-down of PD-L1 inhibited Cyclin D1 and CDK2 (P < 0.05), and Ki67, while promoted Caspase-3 and Bax expressions (P < 0.05) to facilitate cell growth in CR-GC cells in vivo." (PMID 33579380, 2021). "Therefore, when the sample is enlarged and after balancing different tumor types, the value of CCND1's impact on prognosis may be weakened." (PMID 32903763, 2020). "In addition, the western blot data of PC-3-transplanted tumor tissues demonstrated that the protein levels of Sp1, Sp3/4, Survivin, and Cyclin D1 were decreased, while the protein levels of c-Caspase 3 and c-PARP-1 were increased in the HD and PC groups (compared with the NC and LD groups)." (PMID 32851058, 2020). "Importantly, the observation that RB mutation is uncommon in NPC suggests that a blockade of CDK4/6 activity could abolish the dependency of this tumor type on the cyclin D1–RB pathway." (PMID 33243298, 2020). "Thus, CCND1 plays a critical role in promoting tumor development." (PMID 32566661, 2020). "Additionally, to sustain proliferative signalling (right side), the tumour oncogene CCND1, probably influenced by the co-expressed gene NCOA1/3 as well as the suppressors CDKN2A and CDKN2B, which govern the cell cycle, were genetically altered to enhance cancer cell growth in both smoking subgroups." (PMID 32455963, 2020). "Cyclin D1 could be the driver of cell proliferation in this tumor." (PMID 31673890, 2020).
tumor (continued). "In addition, miR-195 and miR-466 expressions could act as a tumor metastasis suppressor and OS progression inhibitor, respectively, via targeting oncogenic CCND1." (PMID 32565738, 2020). "miR-320 overexpression in PCa cells plays a tumor-suppressive role by decreasing PCa tumorigenesis in vitro and in vivo through targeting of lymphoid enhancer-binding factor 1 (LEF1), CD44, SOX9, Oct-4 and CCND1, all associated with the Wnt/β-catenin signaling pathway." (PMID 33426506, 2020). "A growing scientific interest is directed to the role of Cyclin D1 in this complex interplay and how it is correlated with proliferative signaling, cellular energetics, inflammation, angiogenesis, activating invasion, and metastasis all contributing with tumor progression." (PMID 33317149, 2020). "Moreover the miR‐302e‐mediated tumor inhibition could be effectively counteracted by ectopic expression of circ‐CMPK1 or cyclin D1 both in vitro and in vivo." (PMID 31863641, 2020). "Since the repression of cyclin D1 promotes cell cycle exit, cellular quiescence and, in some cases, cell differentiation and, in HNSCC tumor models, reduces cell growth and survival, these findings indicated that a CCND1 decrease may have a positive impact on patient outcome." (PMID 32224897, 2020). "In addition, abundant Cyclin D1 expression in the tumor was observed." (PMID 31673890, 2020). "Thus, a preexisting immune response against tumor cells expressing CCND1 may be boosted by nivolumab treatment and thus eliminate such tumor cells." (PMID 33299117, 2020). "Finally, some oncogene pathways are activated in CCND1 amplification tumor that may lead to acceleration of tumor growth." (PMID 32903763, 2020). "Thus, therapies directed to Cyclin D1/CDK4 may be useful in targeting both the tumor cell and modulating the activity of a stromal cell type that is critical to support malignant progression." (PMID 33317149, 2020). "Indeed, cyclin D1 levels can influence tumour progression, and may have prognostic significance in FTC." (PMID 32093341, 2020). "However, it remains unclear how CCND1 expression changes between tumor and normal tissues and whether human papillomavirus (HPV) affects differential CCND1 expression." (PMID 32224897, 2020). "Furthermore, we found that the GOLPH3-STIP1 interaction was mechanistically associated with the promotion of telomerase reverse transcriptase (hTERT) as well as telomerase activity by c-Myc, which subsequently upregulated cyclin D1 to promote tumor cell growth." (PMID 33134174, 2020). "Furthermore, EGFR and CCND1 CNAs have an additive effect on OSCC tumor progression." (PMID 31159251, 2019). "The tumor promoting role of CORO1C might be mediated by cyclin D1 and vimentin." (PMID 30974047, 2019). "Whether cyclin D1 contributes to glucose metabolism in tumor cells requires further examination." (PMID 30899002, 2019). "Genetic alterations affecting Cyclin D1, and control exit from the G1 phase of the cell cycle, are frequently documented in human cancers and inactivation of this pathway may as well be necessary for tumor development." (PMID 31495785, 2019). "However, the expression of CCND1 was downregulated in tumour samples compared to normal samples." (PMID 30872976, 2019). "Interestingly, CDK4 gene expression was higher in luminal B and basal-like CCND1-amplified tumours only (“CDK4” P = 0.004 and P = 0.029 respectively) whilst CDK6 expression was lower in luminal A, luminal B and HER2-enriched CCND1-amplified tumours (“CDK6” P < 0.001 for all comparisons)." (PMID 30819233, 2019). "Furthermore, combined inhibition of FGFR1 and CDK4/6 in CAMA1 cell line abolished anti-estrogen resistance suggesting that an interaction between FGFR1 and cyclin D1 might drive estrogen-independent proliferation in co-amplified tumours." (PMID 31142340, 2019).